GRIN2A (glutamate ionotropic receptor NMDA type subunit 2A)
Diseases named in the same sentence as GRIN2A in open-access papers (continued):
Sharing a sentence is not in itself a finding about the gene and the disease.
Parkinson disease (30 papers, 2011 to 2025). A progressive degenerative disorder of the central nervous system characterized by loss of dopamine producing neurons in the substantia nigra and the presence of Lewy bodies in the substantia nigra and locus coeruleus. "Genome-Wide Gene-Environment Study identifies Glutamate Receptor Gene GRIN2A as a Parkinson’s disease Modifier Gene, which encodes an NMDA-glutamate-receptor subunit and regulates excitatory neurotransmission in the brain." (PMID 34143809, 2021). "Dopaminergic neuronal degeneration seen in Parkinson's disease (PD) might result from a single nucleotide polymorphism (SNP) in the glutamate ionotropic receptor NMDA type subunit 2A (GRIN2A) gene." (PMID 31942532, 2019). "Our analysis revealed that two GRIN2A variants, rs7192557 and rs8057394, were most frequently associated with dyskinesia in our control group of patients with neurological disorders (101 with Parkinson's disease, 21 with essential tremor, and 21 with different forms of dystonia)." (PMID 27144051, 2016). "Association of coffee drinking with the CT-TT genotype of rs4998386 in the GRIN2A gene among Parkinson disease cases." (PMID 25412286, 2014). "Negative interaction, such as the recently discovered coffee-GRIN2A interaction in Parkinson's disease, increases the power of LT." (PMID 23144628, 2012). "CAF interacts with specific genetic variants such as MAPT, SLC2A13, LRRK2, ApoE, NOS2A, GRIN2A, CYP1A2, and ADORA2A, which may influence the risk of developing Parkinson’s Disease (PD)." (PMID 40650030, 2025). "Mutations in GRIN2A are strongly associated with childhood epilepsy/aphasia syndromes and there is evidence for dysregulation of NMDA receptor subunit composition in Rett Syndrome and in Parkinson’s disease." (PMID 26829109, 2016). "Interestingly, Genome-wide gene-environment study identifies glutamate receptor gene GRIN2A as a Parkinson's disease modifier gene via interaction with coffee." (PMID 26361355, 2015). "Independent and joint effects of coffee drinking and GRIN2A-rs4998386 for Parkinson disease." (PMID 25412286, 2014).
Epileptic encephalopathy (29 papers, 2016 to 2026). A condition in which epileptiform abnormalities are believed to contribute to the progressive disturbance in cerebral function. "This review article exemplary discusses GRIN2A-associated disorders, development-related and epileptic encephalopathies including Dravet syndrome and tuberous sclerosis complex." (PMID 42213102, 2026). "GRIN2A has initially been associated with neurodevelopmental disorders, comprising particularly developmental and epileptic encephalopathy, ID and speech disorders." (PMID 41087560, 2026). "GRIN2A mutations have previously been associated primarily with idiopathic focal epilepsy with incomplete penetrance and, less frequently, with epileptic encephalopathy (EE)." (PMID 40149474, 2025). "Pathogenic variants of PCDH19, SCN8A, KCNQ2, and GRIN2A are associated with distinct forms of developmental and epileptic encephalopathy (DEE), many of which present with DRE." (PMID 40290041, 2025). "Variants in GRIN2A were associated with developmental and epileptic encephalopathy, disorders of the epilepsy aphasia spectrum, speech disorders and schizophrenic psychoses." (PMID 37542675, 2023). "In 17.6% of children with epileptic encephalopathy with continued spike-wave activity during sleep, a mutation of the GRIN2A gene, which encodes the alpha subunit of NMDA receptors, was identified." (PMID 38069426, 2023). "The C1845A mutation on GRIN2A gene encodes for GluN2AN651K variant at the M2 loop leading to low Mg2+ blockade, decrease in Ca2+ permeability both for di-heteromeric and tri-heteromeric NMDARs, and to epileptic encephalopathy with cognitive impairment." (PMID 32102377, 2020). "A child with an early onset epileptic encephalopathy due to this GRIN2A missense mutation (L812 M) was treated with memantine added on to his antiepileptic medication regimen, and had a significant decrease in seizure frequency and improvement in interictal EEG recordings." (PMID 28082152, 2018). "Elevated expression of GRIN2A was observed in the PVALB_RGS5 subtype, and gain-of-function mutations in GRIN2A are linked to N-methyl-D-aspartate receptor overactivation, neuronal hyperexcitability and severe developmental and epileptic encephalopathy phenotypes." (PMID 40313715, 2025). "Landau–Kleffner syndrome (LKS), is a rare, poorly‐understood epileptic encephalopathy with spike–wave activation in sleep associated with mutations in GRIN2A, encoding the N‐Methyl‐D‐Aspartate receptor (NMDAR) GluN2A subunit." (PMID 40944498, 2025). "Pathogenic variants of the GRIN2A are associated with the Landau–Kleffner syndrome (LKS), which is a rare epileptic encephalopathy characterized by language regression and focal epilepsy." (PMID 40290041, 2025). "For example, mutations in GRIN1 are associated with early infantile encephalopathy and developmental delay, while GRIN2A and GRIN2B mutations contribute to epilepsy syndromes like Landau–Kleffner syndrome and epileptic encephalopathy, respectively." (PMID 39596430, 2024). "Research using Grin2a mutant models is instrumental in understanding the pathophysiology of focal epilepsy and epileptic encephalopathy." (PMID 39452036, 2024). "Mutations in the Grin2a gene, which encodes the NMDA receptor’s NR2A subunit, have been associated with a range of neurological disorders, including focal epilepsy and epileptic encephalopathy." (PMID 39452036, 2024). "Mutations in genes encoding NMDAR subunits, such as GRIN1, GRIN2A, GRIN2B, GRIN2C, and GRIN2D, have been linked to various epileptic phenotypes, ranging from focal and generalized seizures to severe epileptic encephalopathies." (PMID 39596430, 2024). "They did, however, exhibit both an increased seizure susceptibility and an increased seizure resistance in response to different electroconvulsive threshold testing, highlighting the biological complexity of GRIN2A involvement in epileptic encephalopathy." (PMID 36232696, 2022).
Epileptic encephalopathy (continued). "Grin2a and Grin2b encodes subunits of the glutamate ionotropic receptor NMDA and their mutations are related to idiopathic focal epilepsy and epileptic encephalopathy, respectively." (PMID 34177758, 2021). "For patients with pathogenic GRIN2A variants leading to NMDAR-GOF change, there are studies which argued that they mostly result in epileptic encephalopathy with more severe ID/DD and have poor prognosis." (PMID 33240831, 2020). "However, GRIN2A can also lead to more severe phenotypes, such as early-onset epileptic encephalopathy." (PMID 31312171, 2019). "Similarly, novel pharmacological agents such as NMDA receptor antagonists for GRIN2A/GRIN2B mutations, KCNQ channel openers for KCNQ2-related epileptic encephalopathies, and IGF-1 analogues for trophic deficiency syndromes signify the forthcoming generation of personalized treatments." (PMID 41470225, 2025). "In the case of a 6-year-old child with GRIN2A mutation and early-onset epileptic encephalopathy, non-responsive to conventional methods of treatment, good response to memantine, an FDA-approved drug used clinically for the treatment of Alzheimer's disease, was observed." (PMID 31312171, 2019).
Stroke (22 papers, 2012 to 2025). Sudden impairment of blood flow to a part of the brain due to occlusion or rupture of an artery to the brain. "We showed that the expression of Dlg4, Gria1, Grin2a, Gng3, Gnb5, MapK8, and Bdnf (encoding PSD-95, GluA1, GluNMDA2A, G-protein subunit gamma 3, G-protein subunit beta 5, JNK, and BDNF, respectively) was strongly reduced 1 week after stroke." (PMID 31888302, 2019). "Importantly, lncRNA RP11-297M9.1 locates in the 3' area of protein-coding gene GRIN2A, whose expression increases immediately after onset of stroke and being highlighted in many other publications on ischemia/reperfusion models." (PMID 30186861, 2018).
autism (16 papers, 2011 to 2024). Persistent deficits in social interaction and communication and interaction as well as a markedly restricted repertoire of activity and interest as well as repetitive patterns of behavior. "In our sequenced cohort of 134 individuals with autism and regression, we identified two recurrent variants, GRIN2A c.28C > A (p.Leu10Met) and PLXNB2 c.742C > T (p.Arg248Cys)." (PMID 32722525, 2020). "The observation of three individuals with probable pathogenic variants in GRIN2A suggests that the dysfunction of GRIN2A may account for a substantial (2.2%) proportion of cases in this sample of individuals with regressive autism." (PMID 32722525, 2020). "In the Simons Foundation Autism Research Initiative (SFARI) database, three genes (BRAF, GRIN2A, MTOR) are identified as strong autism risk genes." (PMID 35883654, 2022).
bipolar disorder (13 papers, 2011 to 2026). A disorder of the brain that causes unusual shifts in mood, energy, activity levels and the ability to carry out day-to-day tasks. "We also identified differentially hydroxymethylated sites in the promoter and distal enhancer-like signature (dELS) regions of GRIN2A, an important regulator of glutamate signaling that has been well associated with bipolar disorder." (PMID 37139321, 2023).
focal epilepsy (13 papers, 2015 to 2024). A seizure caused by a localized disorder. "In particular, mutations of the GRIN2A gene have been found in patients with focal epilepsy and speech disorders, including LKS." (PMID 38397281, 2024). "Patient 6 is heterozygous for a de novo mutation (c.1845T>C) in the gene GRIN2A, which encodes a member of the glutamate-gated ion channel protein family and is associated with focal epilepsy and mental retardation." (PMID 37408271, 2023). "Heterozygous GRIN2A germline variants are considered to be major genetic causes of Landau Kleffner syndrome, which is characterized by speech impairment and focal epilepsy." (PMID 32722525, 2020). "We identified a de novo missense mutation in the GRIN2A gene in a patient with childhood focal epilepsy and acquired epileptic aphasia." (PMID 28182669, 2017). "We identified a de novo missense mutation c.2191G>A (p.Asp731Asn, D731N) in a patient with focal epilepsy and acquired epileptic aphasia, a heterozygous GRIN2A mutation in a portion of the gene that is intolerant to change." (PMID 28182669, 2017). "The archetypal GRIN2A-related phenotype comprises the idiopathic focal epilepsies (IFEs), with a higher incidence of GRIN2A mutants among entities at the more severe end of the spectrum." (PMID 33946630, 2021). "To date, more than 140 GRIN2A mutations have been identified in focal epilepsy with or without speech disorders and EE." (PMID 34720871, 2021).
Landau-Kleffner syndrome (13 papers, 2017 to 2023). A rare form of epileptic encephalopathy with spike-wave activation in sleep (EE-SWAS) characterized by various combinations of acquired cognitive, language, behavioral, and motor deficits associated with marked spike- and- wave activation in sleep. "One patient with Landau Kleffner syndrome and GRIN2A mutation was included after being resistant to corticoids, clobazam, and valproic acid." (PMID 37712338, 2023). "Genetic variants in GRIN2A are a major cause of Landau Kleffner syndrome." (PMID 32722525, 2020). "Moreover, the GRIN2A-related epilepsy-aphasia spectrum is broad and ranges from the mild end, such as CECT, to the severe end, such as Landau-Kleffner Syndrome (LKS) and Continuous Spike and Wave During Sleep (CSWS) in DEE." (PMID 35706428, 2022).
developmental delay (12 papers, 2017 to 2025). "Only two of the 35 samples with rare DAGLA variants harbored a likely pathogenic variant in another gene known to be associated with seizures and developmental delay (GRIN2A in subject 061 and MEF2C in subject 044)." (PMID 29145497, 2017).
Aphasia (11 papers, 2017 to 2025). An acquired language impairment of some or all of the abilities to produce or comprehend speech and to read or write. "While GRIN2A mutations typically manifest in children, our case demonstrates that adults can experience similar symptoms, including behavioral abnormalities, aphasia, and seizures." (PMID 39050322, 2024). "The rapid progression characterized by significant cortical atrophy, seizures, aphasia, and neuropsychiatric abnormalities necessitates further studies to fully comprehend the wide spectrum of GRIN2A mutations." (PMID 39050322, 2024). "We report an unusual presentation of adult-onset GRIN2A mutation-associated progressive limbic encephalopathy (LE), characterized by rapidly progressive cortical atrophy, seizures, aphasia, and neuropsychiatric abnormalities, which ultimately led to the patient’s sudden demise." (PMID 39050322, 2024). "Out of 36 patients from 16 families with epileptic aphasia spectrum due to GRIN2A alterations, two non-related individuals had “autistic features” and CSWSS." (PMID 28649286, 2017).
autism spectrum disorder (11 papers, 2016 to 2025). A spectrum of developmental disorders that includes autism, and Asperger syndrome. "Also, recent studies focused on such pathways, such as a report published in 2022 with two patients with autism spectrum disorders, language delay, cognitive impairment, and focal epilepsy associated with previously reported heterozygous de novo GRIN2A pathogenic variants." (PMID 39596051, 2024).
Dyskinesia (8 papers, 2012 to 2022). A movement disorder which consists of effects including diminished voluntary movements and the presence of involuntary movements. "The GRIN2A variants rs7192557 (rs1969060) and rs8057394 were associated with the age of onset of dyskinesia in Huntington’s disease." (PMID 35885427, 2022). "Other polymorphisms including rs886292 (ABCC8), rs11880894 (RYR1), rs1800497 (DRD2), rs6265 (BDNF), rs11646587, rs7192557 and rs8057394 (GRIN2A) were found to be associated with dyskinesia in patients administered with levodopa medication." (PMID 28927418, 2017). "We have in the past studied the relationship between GRIN2A and GRIN2B variants and the occurrence of drug-induced dyskinesia." (PMID 34685369, 2021).
memory impairment (8 papers, 2014 to 2025). "Spatial learning and memory impairment and Grin2a upregulation suggest that exposure to Tat protein drives adaptation in mPFC, altering the function of circuitry supporting spatial learning and memory." (PMID 38514527, 2024).
cognitive decline (7 papers, 2015 to 2024). "On the other hand, a few works suggested the neuroprotective function of hippocampal astrocytic NMDARs since pharmacological antagonism of GluN2A and GluN2B or knockdown of Grin2a gene exacerbates β-amyloid (Aβ)-induced synaptotoxicity and cognitive decline." (PMID 39519348, 2024). "Genetic enhancement of Grin2b expression increases NMDA receptor-dependent synaptic plasticity and associated learning and memory functions, and hippocampal reductions in Grin2a and Grin2b have been observed in the AD brain, correlating with cognitive decline." (PMID 26221964, 2015). "Our results showed that astrocyte‐specific knockdown of Grin2a significantly counteracted Aβ‐induced compensatory elevation of β‐NGF, with concomitant aggravated memory and cognitive decline." (PMID 34291567, 2021).
Encephalopathy (7 papers, 2012 to 2025). Encephalopathy is a term that means brain disease, damage, or malfunction. "L‐serine, a precursor of the NMDAR co‐agonist, D‐serine, has been trialed in children with encephalopathy associated with LOF GRIN2A/GRIN2B mutations, and reported to improve seizure frequency, behavior, and neuro‐cognitive skills." (PMID 40944498, 2025). "The rapid neuropsychiatric decline and significant atrophy observed in this patient, despite intermittent improvements, shed light on the aggressive nature of LE in the context of GRIN2A mutations and suggest a severe phenotype of GRIN2A mutation-related encephalopathy." (PMID 39050322, 2024).
epilepsy syndrome (7 papers, 2015 to 2023). A syndrome that has a characteristic cluster of clinical features and/or lectroencephalographic (EEG) findings that reflect underlying epileptic activity. "GRIN2A (glutamate ionotropic receptor NMDA [N-methyl-D-aspartate] type subunit 2A): Mutations in the GRIN2A gene have been linked to various epilepsy syndromes, including autosomal dominant epilepsy with auditory features (ADEAF)." (PMID 37927689, 2023). "Genetic alterations of GRIN2A result in phenotypic pleiotropy, predisposing to a broad range of epilepsy syndromes, with an elusive and unpredictable evolution and response to treatment." (PMID 33946630, 2021). "In this study, children with CHD4 mutations presented as CAE, BECTS, and EFS+, similar as several previously reported genes associated with idiopathic epilepsy, such as GABRG2, SCN9A, and GRIN2A,45, 46 suggesting these epileptic syndromes potentially have similar etiologies." (PMID 34109749, 2021).
Obesity (7 papers, 2017 to 2025). Accumulation of substantial excess body fat. "Lastly, the downregulation of GRIN2A in obese subjects could be associated with the tonic control of sympathetic pathway and arterial pressure, and the downregulation of it could be relevant in obesity to maintain blood pressure levels." (PMID 35059043, 2022). "Additionally, the expression of glutamate receptors such as GluR7 and the glutamate ionotropic receptor NMDA type subunit 2A (Grin2a), as well as scaffolding proteins such as Shank2, critical for synaptic plasticity, are altered in such model of obesity." (PMID 41334434, 2025).
psychosis (7 papers, 2023 to 2026). "All 8 of these were a common SNP psychosis risk gene, but only a single gene – GRIN2A – was implicated in psychotic illness as a propsychotic target gene, a rare LoF psychosis risk gene, and a common SNP psychosis risk gene." (PMID 40701976, 2025). "Among the 170 propsychotic target genes, 8 were a high-confidence psychosis risk gene (GRIN2A, DRD2, CYP2D6, CHRNB4, CHRM4, GABBR1, GRM3, CHRNA3)." (PMID 40701976, 2025). "GRIN2A is also implicated in neurodevelopmental disorders and in critical neuronal processes, including synapse formation, highlighting the role of disrupted neuronal communication in this psychotic disorder." (PMID 40943654, 2025). "Multiple lines of evidence suggest that the Glutamate Ionotropic Receptor N-methyl-D-aspartate (NMDA) Type Subunit 2A (GRIN2A) gene plays an important role in the pathobiology of psychotic disorders." (PMID 37107537, 2023). "Since EOP diagnoses may shift as affected children and adolescents develop, it will be especially important for future research to follow this cohort and report on the correlation of GRIN2A with different psychosis spectrum phenotypes over time." (PMID 37107537, 2023). "A subset of 38 GWAS genes was common to all psychiatric disorders considered here; this includes genes such as GRIN2A, DGKI and SHISA9, which were previously known to be involved in multiple psychosis." (PMID 38864245, 2024).